IL4 (interleukin 4)
Diseases named in the same sentence as IL4 in open-access papers (continued):
Sharing a sentence is not in itself a finding about the gene and the disease.
asthma (continued). "Therefore, patients may benefit more from combined blocking of IL-4 and IL-13 with monoclonal antibodies because of the overlapping pathophysiological roles of IL-13/IL-4 in asthma." (PMID 30703143, 2019). "The results of Spearman’s analysis showed that serum IL-10 was positively correlated with IL-4, and sE-selectin was positively correlated with sICAM-1 and sVCAM-1, suggesting that IL-10 and sE-selectin accelerate the development of allergic rhinitis and asthma." (PMID 30344593, 2018). "Moreover, the percentage of IL-4+ Treg cells is related to the asthma control." (PMID 30013989, 2018). "However, they confirmed that dupilumab, a medication simultaneously targeting at both IL-4 and IL-13 via blocking IL-4 receptor, has yielded more consistent results in reducing asthma exacerbations and improving lung function, especially in patients with increased blood eosinophils." (PMID 30050954, 2018). "Moreover, children with asthma had a high IL-4/INFγ ratio related to Th2 inflammation." (PMID 30035104, 2018). "Moreover, IL-37b could significantly suppress the induced concentrations of Th2 and asthma-related cytokines IL-4, IL-6, and IL-13 in lung homogenate of asthmatic human PBMC NOD/SCID mice (all P < 0.05)." (PMID 29988381, 2018). "Typically in asthma, cytokines released by Type 2 T helper (Th2) cells including interleukin-4 (IL-4), interleukin-5 (IL-5), and interleukin-13 (IL-13) as well as cytokines released by Type 1 T helper (Th1) cells such as interferon-gamma are considered to be the main cytokines triggered in asthma." (PMID 30333747, 2018). "Additionally, IL-4 induces the expression of IgE receptors on mast cells and basophils, which bind IgE and subsequently release preformed mediators that are important in asthma pathology." (PMID 29316647, 2018). "In addition, they point to possible targets, such as p70S6K or GRB10, that could be used therapeutically to downmodulate IL-4-mediated inflammatory responses and M2 macrophage polarization and to control type-2-high asthma." (PMID 28721208, 2017). "However, Oral application Lactobacillus rhamnosus GG inhibited allergic sensitization and airway disease in a murine model of asthma by induction of Treg cells, associated with a parallel suppression of the classical Th1-related cytokine (IFN-γ) and Th2-related cytokines (IL-4 and IL-5)." (PMID 28199353, 2017). "In addition, IL-4 induces IgE synthesis in the pathogenesis of asthma." (PMID 28116321, 2016). "Our data demonstrated that reinfected mice showed an increased production of IL-17A, IL-6, TNF-α, IL-4 and IL-5, suggesting a pattern of mixed Th2/Th17 responsiveness, which was previously observed in studies with helminths and also allergic disorders, such as rhinitis and asthma." (PMID 26814713, 2016). "Airway inflammation is essential to the pathogenesis of asthma and is triggered by respiratory viral infections and inhaled allergen, leading to the activation of T helper 2 (Th2) cell differentiation and the secretion of Th2 cytokines such as IL-4, IL-5, and IL-13." (PMID 27274620, 2016). "Indeed, anti-TNF-α therapy has been reported to reduce the expression of MMP-9 as well as that of other inflammatory cytokines (e.g., IL-4, IL-13, and IgE), thereby hindering the recruitment of inflammatory cells and inhibiting the airway inflammation in asthma." (PMID 26783416, 2016). "Further, we have shown that, although a variety of Th2 cytokines as well as IL-25 have been implicated in causing remodelling changes in human and murine airways in asthma, only IL-25, and not IL-4, IL-5 or IL-13 is able directly to induce angiogenesis by human vascular endothelial cells." (PMID 25889697, 2015). "Cytokines other than IL-4 and IL-13 may be responsible for increases in pendrin expression; IL-1β, a macrophage-secreted cytokine involved in the immunopathogenesis of asthma and COPD, has also been shown to increase pendrin levels in rodent and human bronchial epithelial cells." (PMID 26612971, 2015).
asthma (continued). "Furthermore, several reports showed that Th2 cytokines, particularly IL-4 and IL-13, laid at the center of the recruitment of eosinophils and promoting goblet cell metaplasia and hyperplasia, leading to airway mucus hyper-secretion in asthma." (PMID 26343632, 2015). "Additionally, IL-4 and IL-13 act on bronchial epithelial, endothelial and airway smooth muscle cells, collectively leading to many of the pathophysiological features of asthma." (PMID 26362930, 2015). "We hypothesized that interactions between genetic variants and methylation in genes in this pathway (IL4, IL4R, IL13, GATA3, and STAT6) influence asthma risk, that such influences are age-dependent, and that methylation of some CpG sites changes over time in accordance with asthma transition." (PMID 24735657, 2014). "The same study suggested that TLR3 systemically modulated disease development in a rat asthma model by reducing serum IgE release via IL4 down-regulation, which may provide a vital clue for further research in asthma pathogenesis and suggest a new target for asthma treatment." (PMID 23882263, 2013). "Moreover, an increase in the airway hyperresponsiveness of asthma and airway remodeling may be due to increased production of IL-4, IL-5, IL-6, and IL-13 in the inflammated airways." (PMID 23533467, 2013). "Furthermore, many other genes were related to asthma, such as IL-4, IL-5, and PAI-1." (PMID 23841068, 2013). "Therefore, a good example is the IL-4 and IL-13 pathway for anti cytokine treatment against asthma." (PMID 24032029, 2013). "Also, omalizumab significantly reduced RNA and protein levels of IL-6, IL-8,TNFα and IL-4 in a dose-dependent manner in IgE-stimulated human airway smooth muscle cells isolated from biospsy specimens of patients with asthma, chronic obstructive pulmonary disease and healthy controls." (PMID 24004581, 2013). "Thus, IL-2 and IL-4 are likely to be responsible for reduced corticosteroid responsiveness as both cytokines were increased in severe asthma and induced corticosteroid insensitivity in vitro via reduced GR nuclear translocation due to excessive GR serine 226 phosphorylation." (PMID 22911818, 2012). "The suppression of all the symptoms of asthma in the present study was associated with reduced levels of various Th1 cytokines (TNF-α, IL-6, and IL-1β), with reduced levels of various Th2 cytokines (IL-4, IL-5 and IL13) and with reduced levels of a Th17 cytokines (IL-17F) in splenocytes." (PMID 23346203, 2012). "Hence TLR7 in spleen may play a key role in the development of asthma via IL-4 to induce the production of allergen-specific IgE by B cells." (PMID 21364926, 2011). "Moreover, it is well established that there is a strong interaction between eosinophils and Th2 cells in the asthmatic airways and that Th2 cell-derived cytokines, namely IL-4, IL-5, and IL-13, play critical roles in orchestrating and amplifying allergic inflammation in asthma." (PMID 21772663, 2011). "Increased production of IL-4 and IL-13 in both CD4+ and CD8+ T cells accompanied by decreased IFN-γ expression in CD4+ T cells may be evidence that both lymphocyte subpopulations are implicated in the pathogenesis of asthma." (PMID 21197090, 2010). "In an animal model of asthma intratracheally delivered AP-1 decoy oligodeoxynucleotides attenuate eosinophilic airway inflammation, airway hyperresponsiveness, mucous cell hyperplasia, production of allergen-specific immunoglobulins, and synthesis of IL-4, IL-5, and IL-13 in the lung." (PMID 18315837, 2008). "Macrophages treated with Th2-type cytokines such as Interleukin-4 (IL-4) and Interleukin-13 (IL-13) exhibit an altered phenotype and such alternatively activated macrophages are important in the pathology of diseases characterised by allergic inflammation including asthma and atopic dermatitis." (PMID 17134490, 2006).
asthma (continued). "Interleukin (IL)-4 is key factor contributing to the chronic inflammatory state that characterizes asthma and may be involved in the connective tissue alterations that characterize airway remodeling in asthma." (PMID 16472404, 2006). "Given the excess IL-4 observed in asthma we believe that these mechanisms may play an important role in impairing virus clearance and augmenting allergic inflammation in virus-induced asthma." (PMID 16001979, 2005). "Elevated IL-4, IL-9, and TNF-α were observed in non-T2 asthma compared with T2-high asthma, while children exhibited higher levels of IL-2, IL-6, IFN-γ, and IL-17A than adults." (PMID 41601686, 2026). "In asthma mouse models, early RSV infection has also been shown to exacerbate airway inflammation and enhance Th2 cytokine expression, including IL-4 and IL-13." (PMID 41576028, 2026). "Using a house dust mite (HDM)-induced murine asthma model and HDM, IL-4, IL-13, or TNF-α stimulated human primary bronchial epithelial cells (BECs) and bronchial epithelial (Beas-2b) cells, we modulated FAO with L-carnitine (agonist) and Etomoxir (inhibitor)." (PMID 41555513, 2026). "IL‐4 and IL‐13, together with TGF‐β, stimulate the production of periostin, which then promotes fibroblast differentiation and EMT in asthma." (PMID 40777200, 2025). "We showed how this BsAb potently neutralized signaling from TSLP, IL-4, and IL-13; reduced inflammatory responses in human cell-based assays; and provided broader efficacy in a TSLP/OVA-induced asthma model compared with single-pathway blockade." (PMID 41294800, 2025). "Asthma is a T helper 2 (Th2) disease characterised by eosinophilic lung inflammation, mucus production, AHR, Th2 cytokines (interleukin-4 (IL-4), IL-5, and IL-13), and B cells producing IgE." (PMID 41401081, 2025). "In asthma and atopic dermatitis, PAH exposure correlates with Th2-biased cytokine expression and epigenetic modifications at loci such as IL4 and IL13." (PMID 41020825, 2025). "In a previous study, WEIF was revealed to reduce the serum levels of Th2 cytokines (IL-4, IL-5, and IL-13) and IgE in an OVA-induced asthma model by inhibiting the JAK/STAT signaling pathway." (PMID 40806199, 2025). "Central to the eosinophilic inflammation seen in many asthma phenotypes are TH2 lymphocytes, which secrete IL-4, IL-5, and IL-13 in large amounts." (PMID 40732309, 2025). "Publication bias was examined using funnel plots for asthma daytime and nighttime symptom scores, FEV1, FVC, PEF, and the levels of TNF-α, IL-4, and IFN-γ." (PMID 41561940, 2025). "The relevance between the FEO‐03 network and asthma on the KEGG Pathways database presented EPX, IL4, IL5, IL13, CD40LG, TNF, and IL10 according to p value." (PMID 40777200, 2025). "In the HDM mouse model of asthma, SM17 reduced lung pathology score, eosinophil infiltration, and inflammatory cytokine (IL-4, IL-5, IL-13) secretion to levels comparable to dexamethasone-treated mice." (PMID 41409758, 2025). "This suggests that IL-5 may synergize with other cytokines such as IL-4 and IL-13 that are known to have a fibrotic by stimulating airway fibroblasts, further exacerbating airway remodelling, positioning it as a potential therapeutic target for fibrosis-related complications in asthma." (PMID 41188935, 2025). "Dupilumab, a monoclonal antibody targeting IL4/IL13 receptor, has demonstrated its efficacy since 2018 in improving asthma control, lung function, and reducing asthma exacerbation and OCS-dependence in asthmatics with type 2 inflammation." (PMID 41153688, 2025). "In asthma patients, including Th2 cell transcription factor, GATA3 the high levels of Th2-cell related cytokines such as IL-4, IL-5 and IL-13 were observed." (PMID 40323927, 2025). "Two major endotypes are T‐helper type 2 (TH2)‐high asthma, characterized by eosinophilic inflammation and elevated cytokines (IL‐4, IL‐5, IL‐13, IgE), and TH2‐low asthma with neutrophilic or pauci‐granulocytic profiles and corticosteroid‐resistance." (PMID 41185941, 2025).
asthma (continued). "In a more mechanistic approach, using mice that only lack IL-4/IL-13 in T cells, our group showed that cytokines of Th2 cells are responsible for induction of eosinophilia in OVA-induced asthma as well as in an ABPA mouse model." (PMID 40276331, 2025). "Our findings indicated that probiotic supplementation significantly reduced IL-4 levels and increased those of IFN-γ in pediatric patients with asthma." (PMID 41561940, 2025). "The main molecular pathways of asthma include T2 inflammation, mediated by Th2 and ILC2 cells, eosinophils, and the cytokines IL-4, IL-5, and IL-13, as well as non-T2 inflammation, mediated by neutrophils, macrophages, and the cytokines IL-1, IL-6, and IL-17." (PMID 40136501, 2025). "In the later asthma model, YCFA-33 administration significantly increased total IgG and IgG1 in serum, reduced OVA-IgE levels and IL-4 levels, decreased neutrophil content and TNF-α expression, and increased IFN-γ levels in lung lavage fluid (p<0.05)." (PMID 40821771, 2025). "IL-4 and RV infection induced a significant increase in thymic stromal lymphopoietin (TSLP) levels in BECs from asthma compared with healthy, which was normalized by IL-4Rα mAb." (PMID 40370530, 2025). "The S1P2 antagonist JTE-013 decreases eosinophil counts and Th2 cytokine (IL-4, IL-5) levels in BALF in allergen-challenged mice (animal model for asthma)." (PMID 40001485, 2025). "This is consistent with previous work showing that elevated TSLP in lungs correlates with increased AHR in both mouse models and human asthma, and that neutralizing TSLP or downstream cytokines like IL-4 and IL-13 mitigates AHR and airway inflammation." (PMID 41259396, 2025). "In an OVA-induced asthma mouse model, TSG significantly modulated immune responses by suppressing Th2 cytokines, such as IL4 and IL5, and reducing total IgE and OVA-specific IgE levels, which are typically elevated in asthma." (PMID 40598285, 2025). "The following studies demonstrated compromised epithelial barriers in conditions like asthma, atopic dermatitis (AD), and CRS, exposure to barrier‐toxic substances, and the effects of type 2 immune responses, particularly cytokines IL‐4 and IL‐13." (PMID 40679787, 2025). "These conclusions were reflected in the animal asthma model (ovalbumin-treated mice), as CBD therapy led to a decrease of IgE, IL-4, IL-5, and IL-13 levels in both blood and lung tissue, as well as eosinophil and neutrophil infiltration in the lung." (PMID 40244178, 2025). "Compared to the control group, the levels of IL-4, IL-6, IL-8, IL-10, TNF-α, CRP, and TGF-β in the EBC of asthma patients increase simultaneously." (PMID 40558433, 2025). "Reduced ACE-2 expression in the airways of asthma patients may limit viral entry into cells, and the Th2 immune response, prominent in allergic diseases like atopic asthma, could suppress the pro-inflammatory Th1 response via the type 2 cytokines IL-4 and IL-13, offering further protection." (PMID 40004141, 2025). "In the experiment, after OVA stimulation, the levels of IL-4, IL-5, IL-13, and TNF-α in BALF and the level of IgE in the serum of mice in the asthma model group were significantly elevated, indicating that Th2 cells were overly active." (PMID 40563981, 2025). "Meng and Zhu found that administration of recombinant human IL-37 protein, either via intranasal inhalation or intravenous injection, effectively reduced levels of IL-4, IL-5, IL-6, and IL-13 in a chronic HDM-induced asthma model." (PMID 41293155, 2025). "In a TSLP/OVA-induced asthma model with transgenic human TSLP, TSLP receptor, IL-4, and IL-4Rα mice, the BsAb reduced every single allergic/inflammatory hallmark, while the single target blockade antibody failed to have such comprehensive effects." (PMID 41294800, 2025). "Thirdly, although we found that the cytokines or markers, such as IL-33, ST2, IL-4 and MRC1, participated in the treatment of calycosin in asthma, the direct molecular mechanism of action is still unclear." (PMID 38650035, 2024).
asthma (continued). "Preliminary research from our group in an asthma model induced with OVA in BALB/c mice showed that CO treatment regulates eosinophils, neutrophils, and the inflammatory markers IL-4, IL-5, IgE, IL-17, TNF-α, and IFN-γ." (PMID 38666018, 2024). "We found that the mRNA expression of IL-13, TNF, IL-4, VEGFR2 and VEGF, were downregulated in the control, dexamethasone and vandetanib groups compared with the asthma group." (PMID 38799165, 2024). "With regard to asthma, a blockade of TL1A with neutralizing antibodies suppressed airway inflammation and levels of IL-4, IL-5, and IL-13 in a murine model of asthma." (PMID 38540714, 2024). "Administration of crocin (25 mg/kg/day, PO) in mice with asthma induced by OVA resulted in a decrease in levels of TNF-α, IL-4, IL-13, LDH, and MDA, while levels of SOD and GSH in lung tissue were increased." (PMID 38419885, 2024). "To investigate the effect of shikonin on T-cell populations in asthma mice, we evaluated the phenotypes of CD4+ cells in lung tissues by analyzing the expression of IFN-γ, FOXP3, IL-4, and IL-17 via flow cytometry." (PMID 39444792, 2024). "A study revealed that in an ovalbumin (OVA)-induced asthma model, cDC1-induced CD4+ T cells secreted significantly more IL-4, IL-6, and IL-10, whereas cDC1-induced higher frequencies of IFN-γ and IL-17A production by CD4+ T cells." (PMID 39530090, 2024). "Th2-related inflammatory cytokines, such as IL4 and IL5, are increased in asthma patients with RSV infection." (PMID 39632661, 2024). "It is interesting that the level of IFN‐γ remained relatively stable compared with the varying levels of IL‐4, IL‐5, and IL‐13, despite a slight increase in the number of Th1 cells and level of IFN‐γ in the lungs during acute asthma exacerbation." (PMID 38938285, 2024). "IL-4 cytokine levels were measured in the BALF and showed a significant increase in the OVA-induced asthma group, compared with the control group." (PMID 38675190, 2024). "For example, in type 2-high asthma, TH2 cells and ILC2s are significant IL-4, IL-5, and IL-13 sources; furthermore, infiltrating mast cells, eosinophils, and basophils play vital roles in producing type 2 cytokines." (PMID 39439788, 2024). "It is plausible that these recruited NK cells, now differentiated as NK2 cells, will produce cytokines including IL-4, IL-5, and IL-13 and lower antiviral cytokine IFN-γ, leading to asthma exacerbations." (PMID 38216935, 2024). "For example, PLA2 contributes to anti-helminth defense by hydrolyzing membrane phospholipids (Th2-defence, production of IL4 and IL5 cytokines, allergy/asthma)." (PMID 38674024, 2024). "IL-4 and IL-13 also directly induce the production of FENO, which is commonly used as a predictive factor for exacerbation recurrence in asthma, but it isn’t considered in most CRSWNP guidelines." (PMID 38850424, 2024). "Some of the genes that were differentially methylated were observed to be differentially methylated in other studies of asthma as well, such as RUNX3 and IL4." (PMID 39380119, 2024). "Using GEO datasets and in vitro cultured HBECs, we uncovered that WNT5A (Wnt5a) is highly enriched in the HBECs from asthma patients, lung of asthma mice, and HDM or IL-4-treated HBECs." (PMID 38898476, 2024). "The concentrations of cytokines such as IL-4, IL-5, IL-13, and TSLP in serum, sputum, and bronchoalveolar lavage fluid (BALF) in asthma have been reported to range from 1 to 100 pg/ml (approximately 0.7–70 pM)." (PMID 39624446, 2024). "Key molecular pathways of refractory asthma include T2 inflammation mediated by Th2 and ILC2 cells, eosinophils, and cytokines including IL-4, IL-5, and IL-13." (PMID 39194521, 2024). "Then, we assessed the levels of IgE, Th2 cytokines (IL-4, IL-5, and IL-13), eotaxin, TGF-β1, and MUC5AC using ELISA kits to detect the effect of scutellarin on the release of asthma-related cytokines in ovalbumin-challenged mice." (PMID 38168709, 2024).